BRCA1 (BRCA1 DNA repair associated)
Diseases named in the same sentence as BRCA1 in open-access papers (continued):
Sharing a sentence is not in itself a finding about the gene and the disease.
breast cancer (continued). "However, mutations in the BRCA1 gene are also present in sporadic breast cancer, including the most difficult cases to treat—triple-negative breast cancer." (PMID 33671579, 2021). "Evidence showed that pathogenic mutations in non-BRCA HRR genes could also help identify susceptibility to familial breast cancer and showed PARPi sensitivity similar to BRCA1/2." (PMID 34917121, 2021). "In addition, patients with PALB2 mutation should be offered breast cancer surveillance similar to that for BRCA1/2 carriers." (PMID 34439348, 2021). "Furthermore, PALB2 is the most frequently altered gene (1.2%) in non BRCA1/2 mutated male breast cancer patients, accordingly the risk of MBC increases from 9.63 to 17.30-fold in presence of PALB2 pathogenetic variants." (PMID 33718150, 2021). "To assess the application of radiotherapy to BRCA1-associated breast cancer, we examined the benefit of radiation to suppress the progression of Brca1-mutant tumors from Brca1co/coMMTV-Cre mice, which develop tumors that mimic human BRCA1 mutation-related mammary tumors." (PMID 33767581, 2021). "Therefore, from breast cancer studies, it was first derived that men with BRCA1 and BRCA2 mutations were at higher risk for PCa." (PMID 34830851, 2021). "As in a recent breast cancer study, the tumour suppressor gene BRCA1 and particularly the single-nucleotide variants (SNVs) in this gene’s exons are focused on understanding the functionally critical domains of BRCA1 and the related clinically actionable genes." (PMID 34078284, 2021). "The identification of the first breast cancer susceptibility genes dates back to the nineties when linkage studies led to the identification of the BRCA1 and BRCA2 genes (BReast-CAncer susceptibility gene 1 and 2) carrying likely pathogenic variants that co-segregate with breast cancer in families." (PMID 34439109, 2021). "Similarly, a large number of breast cancer-prone regions (BCCRs) have been observed for BRCA1/2 and are associated with a relative increase in breast cancer risk and a relative decrease in ovarian cancer risk." (PMID 32862296, 2021). "Such inter- and intra-tumor heterogeneity could also be observed in human breast cancers carrying BRCA1 mutations." (PMID 34815798, 2021). "Brca1 is involved in DNA repair and is linked to cancers, especially breast cancer." (PMID 34938502, 2021). "Moreover, BRCA1 carriers have a 27% risk of developing contralateral breast cancer within 5 years from the initial diagnosis." (PMID 34572941, 2021). "On the other hand, BRCA1 mutated breast cancer cells have been hypothesized to be sensitive to RXR and VDR modulating drugs." (PMID 33478016, 2021). "It is shown that mutations in the BRCA1 gene can easily cause breast cancer." (PMID 33407485, 2021). "Younger, pre-menopausal patients may undergo mastectomy to lower their risk of ipsilateral breast cancer recurrence from somatic or inherited genetic alterations such as BRCA1/2 germline mutations." (PMID 33689057, 2021). "While BRCA1-associated tumors are most commonly a high-grade invasive ductal carcinoma of no special type and the majority fall into the “basal-like” subtype of breast cancer, the BRCA2-associated tumors are very similar to sporadically occurring “luminal-type” tumors." (PMID 33540843, 2021). "BRCA1 or BRCA2 are recurrently mutated in cancers of the breast, ovary, pancreas or prostate." (PMID 34750509, 2021). "The presence of BRCA1 and 2 mutations may predispose to a higher risk of breast cancer in the percentage of 60 and 30% respectively." (PMID 34706754, 2021). "Three genetic factors are involved in breast cancer progression: high penetrance genetic mutations such as those in the BRCA1 and BRCA2 genes, intermediate penetrance variants such as those in ATM, BARD1, PALB2, and CHECK2 genes, and low-penetrance variants such as SNPs." (PMID 34493284, 2021).
breast cancer (continued). "In BRCA1-associated breast cancer, a clinical trial showed that progression-free survival at a median follow-up of 14 months was 2.8 months longer and the risk for disease progression or death was 42% lower with AZD2281 monotherapy compared with conventional chemotherapy." (PMID 33767581, 2021). "Moreover, the same study reported a loss of caveolin-1 (a marker for breast cancer progression) in CAFs, attributed to mutations of BRCA1 as a result of high glycolysis in stromal cells." (PMID 34822416, 2021). "To examine whether radiotherapy could effectively suppress BRCA1-associated breast cancer, we tested the efficacy of X-ray radiation in an in vivo allograft model." (PMID 33767581, 2021). "Therefore, PARP inhibitors have the ability to prevent self-repair in BRCA1/2 mutated breast cancer cells and accelerate apoptosis of tumor cells, thereby enhancing the efficacy of chemotherapy as well as radiotherapy." (PMID 34198652, 2021). "However, germline structural variants are less frequent in breast cancer genes such as BRCA1 (0.8 to 6.9%) and BRCA2 (5%) in Asian populations." (PMID 34857041, 2021). "Meanwhile, mutations of BRCA1 have also been identified in other subtypes of breast cancers." (PMID 34815798, 2021). "Breast cancer risk for BRCA1/BRCA2 mutation carriers varies depending on other genetic factors." (PMID 33597508, 2021). "Patient 13 also carried the LPath variant c.4358-2A>G in the BRCA1 gene, which could play a more crucial role in the development of this patient’s breast cancer." (PMID 33558524, 2021). "Thus, the overall lifetime risk of breast cancer for women carrying a BRCA1/2 mutation is between 50% and 80%, while the lifetime risk for ovarian cancer is 15% to 40%." (PMID 34070748, 2021). "Although not statistically significant, higher incidence of developing contralateral breast cancer for BRCA1/2 mutation carriers who underwent ipsilateral surgery-only compared to those who underwent contralateral RRM was observed [12.1% (95% CI: 7.7–17.7%)] (p = 0.1618)." (PMID 34285295, 2021). "Although hereditary breast cancer is mainly associated with BRCA1/2 pathogenic variants, it may also be associated with germline mutations in other genes." (PMID 33959510, 2021). "In this context, a nutriepigenetic pilot study is being conducted to evaluate how a personalized nutritional and lifestyle intervention (NLI) can modulate expression of blood and salivary miRNAs associated with breast cancer risk in unaffected young women (<40 years) with BRCA1/2 mutations." (PMID 34552867, 2021). "The aim of this study was to examine whether preoperative diagnosis of BRCA1/2 mutation status could influence surgical decision-making in newly diagnosed breast cancer patients." (PMID 34285295, 2021). "This may in part be due to the low frequency of deleterious somatic mutations of BRCA1/2 of ~3% in all breast cancers, in comparison to 19% in ovarian cancers." (PMID 34959671, 2021). "However, when correlating cyclin E protein levels to BRCA1/2 mutations, studies in both ovarian and breast cancer patients show a significant level of correlation." (PMID 33916118, 2021). "Additionally, breast cancers with alterations of cyclin E have a higher prevalence of germline BRCA1/2 mutations than other patients." (PMID 33916118, 2021). "The high risk of contralateral breast cancer may outweigh the benefits associated with BCT for BRCA1/2 variant carriers." (PMID 33890992, 2021).
breast cancer (continued). "To determine the similarity of cellular phenotype of Brca1 and Gata3 deficient tumor cells, we generated five p18mt;Brca1+/-, five p18mt;Gata3+/-, and three p18mt tumor cell lines, each of which was derived from a primary mammary tumor developed in an individual mouse." (PMID 34373738, 2021). "Women who carry these germline mutations are not only diagnosed more frequently with breast cancer but also are diagnosed at an earlier age2, for example, BRCA1 mutation (BRCA1mut) carriers are estimated to have more than a 70% lifetime risk of a breast cancer diagnosis." (PMID 35187501, 2021). "Reduced expression of BRCA1 leads to increased risk of breast cancer development." (PMID 34178980, 2021). "BRCA1 mutation was also detected in 6 of 13 women with previously detected primary breast cancer." (PMID 33478551, 2021). "When Sox11 levels were reduced in one Brca1-deficient mammary tumour cell line that expressed both epithelial and mesenchymal markers, similar effects on proliferation, stem cell activity and expression of lineage markers to those seen in the embryonic mammary progenitor cells were observed." (PMID 33969421, 2021). "According to a large-scale international joint consortium, it was shown that histopathological features of breast cancer refine the likelihood estimation for BRCA1 or BRCA2 variant status, which can be informative for genetic testing and clinical management of the patients involved." (PMID 35008774, 2021). "TNBC is associated to BRCA1/2 at a higher rate than the rest of the breast cancer types." (PMID 34072659, 2021). "Thus, given the numerous hurdles encountered by efforts to develop and validate suitable therapies in clinical trials, a means for improving the treatment of BRCA1-associated breast cancer is urgently needed." (PMID 33767581, 2021). "Consistent with previous reports, germline and, to a lesser extent, somatic BRCA1 mutations were associated with basal breast cancer phenotype-related functional gene sets, while germline and somatic BRCA2 mutations were associated with luminal phenotype-related gene sets." (PMID 33525353, 2021). "The report stated that receiving diagnostic radiation before the age of 30 years old is associated with the increased risk of breast cancer in BRCA1 or BRCA2 carriers, and the dose level is much lower than the increased risk in other groups exposed to radiation." (PMID 33932123, 2021). "Newfound roles and relationships between other DNA repair mechanisms and PARP have been discovered since the release of the PARPis, which could explain the susceptibility of BRCA1/2 breast cancer malignancies to PARPi therapy." (PMID 34070674, 2021). "Due to the high incidence of breast cancer worldwide and its relatively high mortality and morbidity, it is important to implement appropriate screening tests which enable rapid and efficient mutation screening in the BRCA1 and BRCA2 genes." (PMID 33918338, 2021). "Both human individuals with heredofamilial BRCA1 mutations and BRCA1-deficient mouse models stochastically develop mammary tumors 8, 42-44, indicating multiple factors might contribute to the oncogenic process and lead to great heterogeneity of the tumors." (PMID 34815798, 2021). "Xenograft studies demonstrated two-fold increase in tumor growth when the human MDA-MB-231 breast cancer cells were co-injected alongside BRCA1 knocked-down fibroblasts into nude mice, thus, demonstrating the potential effects of BRCA1-deficient tumor stroma on breast cancer growth and invasion." (PMID 35008272, 2021). "Both PABL2 and BRCA1/2 mutation carriers had strong family histories of breast cancer." (PMID 34439348, 2021). "As poly-(ADP)-ribose polymerase (PARP) inhibition is synthetic lethal with the deficiency of DNA double-strand (DSB) break repair by homologous recombination (HR), PARP inhibitors (PARPi) are currently used to treat breast cancers with mutated BRCA1/2 HR factors." (PMID 34439286, 2021).
breast cancer (continued). "In particular, BRCA1-associated breast cancer often appears as a fibroadenoma or cyst on US." (PMID 34674065, 2021). "Furthermore, we identified data from five publications on breast cancer risk associated with HRT use in BRCA1/2 mutation carriers undergoing RRBSO." (PMID 33885953, 2021). "Unfortunately, the patient cancer history or tamoxifen exposure was not well documented for the TCGA-UCEC cancer cohort used in this study, hence we were unable to assess the possible contribution of tamoxifen for BRCA1 or other genes that confer breast cancer risk." (PMID 33917078, 2021). "The same kind of genetic background may also apply to breast cancers, for which BRCA1 and BRCA2 are prominent predisposing genes for the early onset component but at higher ages other genes are likely to contribute." (PMID 34503195, 2021). "For some women, the results of FFPE BRCA1/2 testing in their deceased relative meant their lifetime risk of breast cancer assessment was reduced to either ‘moderate’ risk or ‘population’ risk and the recommendations for the level of breast screening they were eligible for was adjusted appropriately." (PMID 33654310, 2021). "Women at increased risk of breast cancer, including women with a BRCA1/2 pathogenic variant, may also consider use of selective oestrogen receptor modulators (e.g. tamoxifen) as a risk-reducing strategy." (PMID 33836815, 2021). "In breast cancer, it seems that heterozygous BRCA1-mutated microenvironment in germline BRCA1 mutation carriers may significantly contribute to breast cancer development by creating a pro-tumorigenic niche." (PMID 33540843, 2021). "Several attempts were performed whether BRCA1/2 mutation carriers with radiotherapy display higher incidence of secondary malignancy comparing BRCA1/2 mutation carriers with mastectomy or sporadic breast cancer patients." (PMID 33767581, 2021). "Therefore, cells with compromised or at least significantly deficient DNA repair capacity, such as in BRCA1/2 breast cancers, show increased sensitivity to these agents." (PMID 34070674, 2021). "BRCA1/2 pathogenic variant heterozygotes in this study were selected based on having a first breast cancer; these women will have on average a higher PRS, but also higher frequencies of other genetic and nongenetic risk factors than women who do not develop breast cancer at all." (PMID 34113011, 2021). "The correlation between TNBC, basal-like breast cancer, and BRCA1 mutations suggests a similar underlying molecular pathogenesis that could be exploited therapeutically." (PMID 33753748, 2021). "BRCA1/2 can also serve as biomarkers since reduced expression of BRCA1/2, due to mutations or epigenetic inactivation, leads to impaired mammary gland differentiation and increased risk of breast cancer development." (PMID 33916118, 2021). "One gene identified is exceptionally well-known for its role in double-strand break repair and tumor suppression, Brca1; loss of Brca1 function has been associated with increased breast cancer incidence and metastasis, which demonstrates its critical function in maintaining stability." (PMID 33419422, 2021). "Similarly, BRCA1 mutation has recently been associated with POI but has long been screened at clinics as a marker of risk of developing breast cancer." (PMID 34193292, 2021). "To determine whether the combination of irradiation and PARP inhibition is effective in suppressing BRCA1-deficient breast cancer, we first tested the efficacy of irradiation together with AZD2281 in MCF7 cells transfected with siRNA against BRCA1." (PMID 33767581, 2021).
breast cancer (continued). "Moreover, the early identification of women who carry pathogenic or likely pathogenic germline variants in BRCA1 or BRCA2 genes will allow the setup of an appropriate diagnostic-therapeutic path to improve the overall survival rate of breast cancer patients." (PMID 34717758, 2021). "Interestingly, mutated BRCA1 in breast cancer cells is associated with β-hCG overexpression, which results in pluripotency and EMT." (PMID 34359928, 2021). "RAD52 is shown to be associated with breast cancer susceptibility genes BRCA1 and BRCA2." (PMID 34484285, 2021). "However, the breast cancer risk for BRCA1/2 mutation carriers is only 35%–49% in women from Australia, the UK, and the Republic of Korea3,63,64." (PMID 34570441, 2021). "The ENIGMA (Evidence-based Network for the Interpretation of Germline Mutant Alleles) consortium has been playing an important role to evaluate the clinical significance of sequence variants in high-risk breast cancer genes including BRCA1 and BRCA2 genes since its establishment in 200913." (PMID 34045478, 2021). "Approximately, 85–90% of hereditary BRCA1-mutation carriers will develop breast cancer and the majority of these cases demonstrate an aggressive breast tumor phenotype—basal-like, triple-negative {ER(−), PR(−) HER2(−)}, which is associated with a strong stromal reaction." (PMID 33513753, 2021). "The genetic predisposition to breast cancer may be associated with a mutation in particular genes such as gene BRCA1/2." (PMID 34354733, 2021). "Olaparib is effective in breast cancer patients with BRCA mutations (BRCA1 or BRCA2)." (PMID 34359598, 2021). "In addition, BRCA1/2 variants can increase the risk of second primary breast cancer and other solid tumors such as high-grade serous ovarian cancers, pancreatic adenocarcinoma, and melanomas." (PMID 33507482, 2021). "Also, albeit uncommon, either BRCA1 or BRCA2 mutation has been detected in women with NF1 who develop breast cancer." (PMID 33954070, 2021). "Notably, the expression of these chemokines and the infiltration of monocyte lineage cells were also correlated with the ROS levels in BRCA1 mutation-associated human breast cancer tissues in the same study." (PMID 33498875, 2021). "Up to now, not much attention has been paid to how the cellular components of the TME carrying the germline mutation, such as the BRCA1/2 gene, might affect the development of breast cancer and its progression." (PMID 33540843, 2021). "We suggest that BRCA1 mutated breast cancer cells can develop PARPi resistance by downregulating the EMI1 gene which could be triggered via p21." (PMID 33412559, 2021). "On the other hand, in recent years, as genetic knowledge about ovarian cancer has rapidly increased, poly (ADP-ribose) polymerase (PARP) inhibitors were introduced to treat ovarian cancer, and promising results were shown in patients with breast cancer gene 1 and 2 (BRCA1/2) mutation carriers." (PMID 33652933, 2021). "In this study, we examined whether BRCA1 loss and cyclin E1 gain occurred concurrently or independently in breast cancer." (PMID 34465787, 2021). "However, they increased the thromboembolic risk as well as the risk of breast cancer development among BRCA1/2 carriers." (PMID 34064977, 2021). "Therefore, the breast cancer patients included in the analyses are likely to be at higher contralateral breast cancer risk when compared with the general BRCA1/2 heterozygote breast cancer population." (PMID 34113011, 2021). "Breast cancer susceptibility in BRCA1/2 mutation carriers may be related to the aberrant expression of certain miRNA clusters." (PMID 34552867, 2021). "Of note, BRCA1/2 germline mutational status is routinely evaluated for the selection of advanced breast cancer patients who may benefit from the poly-adenosine diphosphate–ribose polymerase (PARP) inhibitors olaparib and talazoparib." (PMID 34281208, 2021). "In a Polish cohort, BRCA1/2 mutations were present in as many as 29.6% of bilateral breast cancers." (PMID 34574977, 2021).